ZHX2 (zinc fingers and homeoboxes 2)
Diseases named in the same sentence as ZHX2 in open-access papers (continued):
Sharing a sentence is not in itself a finding about the gene and the disease.
tumor (continued). "In addition, ZHX2 expression is down-regulated in multiple myeloma, and is negatively correlated with tumor proliferation and invasion." (PMID 37460540, 2023). "As E-cadherin is considered a suppressor of tumor metastasis, we ask whether low ZHX2 levels can switch mesenchymal cells to a lower metastatic phenotype." (PMID 37460540, 2023). "Moreover, the patients with reduced ZHX2 nuclear expression have poor tumor differentiation, larger sizes, and a significantly shorter survival time." (PMID 36232466, 2022). "Interestingly, a lower nuclear ZHX2 expression and a higher cytoplasmic ZHX2 expression were found in HCC tissues, but a higher nuclear ZHX2 expression and lower cytoplasmic ZHX2 expression were found in adjacent non-tumor tissue." (PMID 36232466, 2022). "Therefore, ZHX2 is abnormally expressed in multiple tumors and plays different roles, either acting as a tumor suppressor or oncogene in a context-dependent manner." (PMID 36465389, 2022). "Vice versa, increasing LPL expression in HCC cells could reverse ZHX2-mediated cell proliferation inhibition, tumor growth in a xenograft mouse model, lipid metabolism, and tumor formation in mouse liver." (PMID 36232466, 2022). "Whereafter, abnormal expression of ZHX2 is reported in multiple types of tumor." (PMID 36465389, 2022). "These suggest that ZHX2 contributes to hepatocarcinogenesis as a tumor suppressor." (PMID 36465389, 2022). "ZHX2 in cancer-a context-dependent tumor repressor or driver?" (PMID 36465389, 2022). "In addition, ZHX2 inhibited tumor growth in terms of the reductions in growth rate, tumor size and weight, and PCNA-positive cell numbers." (PMID 36232466, 2022). "The results showed that ZHX2 knockdown increased the lung weight and promoted the formation of lung metastatic tumours, displayed as heavier lungs, larger migrated areas and more metastatic tumours in the shZHX2 group than in the shNC group." (PMID 35151335, 2022). "This indicated the critical tumor-inhibitory roles of nuclear ZHX2 in HCC progression." (PMID 36232466, 2022). "The important role of ZHX2-mediated pro-inflammatory polarization of macrophages suggests that targeting ZHX2 to modulate TAM may be a promising strategy for anti-tumor immunotherapy." (PMID 36465389, 2022). "In line with in vitro data, RT‐qPCR analysis of HCC para‐tumor tissues displayed a markedly positive correlation between ZHX2 and LINC01431 expression, and the levels of pgRNA in HCC patients with ZHX2lowLINC01431low were significantly higher than those in ZHX2hiLINC01431hi patients." (PMID 35398991, 2022). "ZHX2 was also indicated to be a tumor suppressor in Hodgkin lymphoma or myeloma although there is no direct experimental evidence supporting this hypothesis." (PMID 34779768, 2021). "The tumor is heterogeneous and the difference in ZHX2 expression in diverse tissues might provide new insights into the function and mechanism of ZHX2." (PMID 33837660, 2021). "Whether ZHX2 could remodel the tumor microenvironment in a TGF‐β dependent pathway in CD4+ T cells requires further exploration." (PMID 33837660, 2021). "(HR = 0.567, p = 0.035), which means ZHX2 might act as a tumor promoter that contributed to occurrence and recurrence of ccRCC." (PMID 32382017, 2020). "Furthermore, ZHX2 overexpression suppressed the growth of xenograft tumors, while ectopic expression of LPL enhanced tumor growth, and clearly reversed the ZHX2-inhibited xenograft tumor growth." (PMID 31740790, 2020). "Notably, LPL overexpression induced by AAV-LPL not only increased the number of tumor nodes but also reversed the inhibitory effect of ZHX2 on tumor formation in STZ–HFD mice." (PMID 31740790, 2020). "It is unclear whether ZHX2 inhibits de novo lipid synthesis to exert its tumor suppressor function in HCC, which will be an interest research direction." (PMID 31740790, 2020). "This indicates that ZHX2 functions as a tumor suppressor in HCC." (PMID 25473899, 2015).
tumor (continued). "TUNEL staining confirmed that ZHX2 promoted CDDP-induced apoptosis of tumor cells." (PMID 25473899, 2015). "However, ZHX2 has been verified as a tumor suppressor in HCC." (PMID 37563132, 2023). "Moreover, although ZHX2 has been identified as a tumor suppressor gene in HCC and can promote chemotherapy sensitivity in HCC, its role in regulating the l-125-induced anticancer effects remains unclear." (PMID 37563132, 2023). "Furthermore, we also analyzed the relationship between ZHX2 and the marker genes of immune infiltration cells, including CD8+ T cells, B cells, T cells (general), monocytes, tumor‐associated macrophages, M1 macrophages, M2 macrophages, natural killer cells, neutrophils and dendritic cells." (PMID 33837660, 2021). "In tumor biopsies of patients with clear cell renal cell carcinoma (ccRCC) and confirmed VHL loss of function mutations, the authors could show a greater amount of ZHX2 (also of HIF-1α and -2α) in the majority of tumors compared to normal kidney tissue." (PMID 31035491, 2019). "When ZHX2 is depleted, it hinders the growth and invasion of TNBC cells in vitro as well as orthotopic tumor growth and spontaneous lung metastasis in vivo." (PMID 38396737, 2024). "Therefore, ZHX2 might play different roles in tumour metastasis depending on the tumour type." (PMID 35151335, 2022). "ZHX2 suppresses the transcription of oncofetal genes AFP and glypican 3 (GPC3), and works as a tumor suppressor gene in HCC." (PMID 36465389, 2022). "Elevating ZHX2 expression can suppress HCC cell multiplication, colony formation, and mice tumor size." (PMID 36232466, 2022). "In this study, we found that low expression of ZHX2 led to upregulation of S100A14, which in turn promoted cell migration, wound healing and lung metastatic tumour formation." (PMID 35151335, 2022). "Functionally, depletion of ZHX2 inhibited TNBC cell growth and invasion in vitro, orthotopic tumor growth, and spontaneous lung metastasis in vivo." (PMID 34779768, 2021). "(G, H) Representative immunohistochemistry (IHC) staining images (G) and quantification (H) of ZHX2 protein level in paired TNBC patient-derived normal and tumor breast tissues." (PMID 34779768, 2021). "Taken together, all these data suggest that, as the transcriptional target of ZHX2, LPL not only mediates lipids uptake of HCC cell lines but also promotes HCC tumor growth." (PMID 31740790, 2020). "ZHX2 overexpression decreased Ki67+ cells, while ectopic LPL elevated Ki67+ tumor cells and restored Ki67 expression in ZHX2 tumor cells." (PMID 31740790, 2020). "The present study has established the ZHX2-LPL axis that maintains hepatocytic lipid homeostasis, hampers NAFLD development and NAFLD–HCC progression, and suppresses HCC tumor growth." (PMID 31740790, 2020). "ZHX2 has been reported to function as a tumor suppressor in the development of HCC and the reduced ZHX2 level also leads to a lower response to chemotherapeutic drugs." (PMID 31582720, 2019). "Additionally, YAP inhibits NF-κB pathway and ccRCC growth by opposing zinc fingers and homeoboxes protein 2 (ZHX2), a critical p65 co-activator, further demonstrating its tumor-suppressive role in ccRCC." (PMID 40673277, 2025). "To validate the clinical relevance of ZHX2 expression, we conducted immunohistochemistry (IHC) staining for ZHX2 on a TNBC tissue microarray (product number: ZL-Brc3N961) containing 48 pairs of TNBC specimens and the corresponding tumor-adjacent tissues." (PMID 37460540, 2023). "Collectively, multiple upstream molecules, such as HDGF, AATF, ZHX2, ACSL4, SPIN, HBx, HDAC8, and STAT5, can regulate SREBP-1 expression, activation, and stability to promote HCC proliferation, invasion, and migration for tumor growth and metastasis." (PMID 35912181, 2022).
tumor (continued). "Therefore, although most studies support the conclusion that ZHX2 works as a tumor suppressor in HCC, the exact role of ZHX2 in HCC needs to be further defined and ZHX2 expression in non-parenchymal cells should be deeply investigated." (PMID 36465389, 2022). "ZHX2 is initially identified as an AFP repressor and a tumor repressor in HCC." (PMID 36465389, 2022). "IHC assays showed that ZHX2 depletion mainly affected proliferation for the tumor cells reflected by marked decrease of Ki-67 in ZHX2 depleted tumor, rather than angiogenesis or apoptosis." (PMID 34779768, 2021). "Importantly, LPL overexpression significantly reverses ZHX2‐mediated inhibition of HCC cell proliferation, xenograft tumour growth, lipid deposition and spontaneous liver tumour formation." (PMID 33630390, 2021). "Immunohistochemistry analysis showed that ZHX2 was not highly expressed in ccRCC tumor tissues, only 33.2% (119/358) patients have high ZHX2 expression." (PMID 32382017, 2020). "Importantly, LPL overexpression significantly reversed ZHX2-mediated inhibition of HCC cell proliferation, xenograft tumor growth, lipid deposition, and spontaneous liver tumor formation." (PMID 31740790, 2020). "Although it is now well established that ZHX1 and ZHX2 worked as tumor suppressors, the role of ZHX3 in cancer is not clear." (PMID 31856408, 2020). "The combined effect of ZHX2 and CDDP in the inhibition of tumor growth in vivo further supports the hypothesis." (PMID 25473899, 2015). "In order to detect whether ZHX2 and CDDP could cooperate to inhibit tumor growth in vivo, HepG2.2.15 xenograft tumors were treated with CDDP and/or plasmid DNA (pcDNA3.0 or pcZHX2)." (PMID 25473899, 2015). "Next, to examine the ability of ZHX2 to maintain TNBC tumor growth in vivo, we first constructed firefly luciferase stably expressing MDA-MB-231 cells (MDA-MB-231-luc) followed by infecting these cells with doxycycline (Dox)-inducible control or ZHX2 shRNAs (Teton sh43, sh45)." (PMID 34779768, 2021). "Finally, xenograft tumor experiments in nude mice showed that compared with the control group, the volume of xenograft tumors in HNRNPD(−), ZHX2(+), linc00707(−) group, as well as the combination of the three were significantly decreased and associated with longer survival period." (PMID 33542193, 2021). "Similarly, ectopic ZHX2 expression reduced HCC cell and tumor xenograft growth in mice." (PMID 28152006, 2017).
cancer (21 papers, 2015 to 2025). A tumor composed of atypical neoplastic, often pleomorphic cells that invade other tissues. "Among the identified transcriptional factors, ZHX2 stands out because it has been known that ZHX2 is a transcription factor associated with a variety of cancers." (PMID 37460540, 2023). "The engineered deletion of ZHX2 caused decreased anti-apoptosis-associated multiple gene expression and inhibited cancer cell growth, metastasis, and metabolism." (PMID 36232466, 2022). "Pharmacological inhibition of Hippo kinase blocked NF-κB transcriptional program and suppressed ccRCC cancer cell growth, which can be rescued by overexpression of ZHX2 or p65." (PMID 38979373, 2025). "To test this possibility, we overexpressed ZHX2 or p65 in 786-O cells via lentiviral infection and measured cancer cell growth in 2D cultures as well as NF-κB target gene expression in the absence or presence of XMU-MP-1 treatment." (PMID 38979373, 2025). "Using advanced techniques, researchers found that ZHX2 collaborates with HIF-1α on specific gene promoters, promoting gene expression linked to cancer." (PMID 38396737, 2024). "ZHX2 is involved in a variety of pathological conditions, including cancer, atherosclerosis, and other metabolic-related diseases." (PMID 37460540, 2023). "A growing number of genes have been identified as the ZHX2 targets, most of which are cancer-related." (PMID 36465389, 2022). "Subsequent studies have found that ZHX2 is widely expressed and participates in many types of cancer." (PMID 36465389, 2022). "ZHX2 enhances the cytotoxicity of anti-cancer drugs in HCC via transcriptional repression of MDR1 leading to decreased drug efflux." (PMID 36465389, 2022). "Consistent with the oncogenic effects of PART1 in the TNBC cells, PART1 knockdown downregulated MYO5A, ZHX2 and BICC1, which have all been implicated in cancer progression." (PMID 34072264, 2021). "From a genomic perspective, it is known that ZHX2 is located on 8q24, a chromosomal region frequently amplified in cancers." (PMID 34779768, 2021). "Experimental evidence points to the role of Zinc fingers and homeoboxes protein 1 and 2 (ZHX1 and ZHX2) in the development and progression of several types of cancer, including hematological malignancies." (PMID 33541423, 2021). "Given that ZHX2 inhibitors are still not available at this time, these peptide inhibitors can be used as a proof-of-principle approach to motivate further development of specific ZHX2 inhibitors in potential cancer therapies." (PMID 34779768, 2021). "The enrichment of KEGG analysis showed several cancer-related pathways were activated in ZHX2 overexpression cells, especially MAPK signaling pathway." (PMID 32382017, 2020). "Increased ZHX2 levels led to reduced drug efflux and enhanced the cytotoxicity of anti-cancer drugs in HCC cell lines." (PMID 25473899, 2015). "Importantly, ZHX2 or p65 overexpression significantly rescued ccRCC cell growth and NF-κB target gene expression after XMU-MP-1 treatment, lending further support that YAP inhibits ccRCC cancer cell growth by opposing the cooperativity between p65 and ZHX2." (PMID 38979373, 2025). "The recent finding that ZHX2 is a VHL substrate that promotes ccRCC cancer progression by forming a complex with p65 to regulate NF-κB target genes let us to speculate that YAP may target the p65-ZHX2 signaling axis." (PMID 38979373, 2025). "If Yap activation inhibits ccRCC cancer cell growth in 2D cultures by impeding p65/ZHX2 cooperativity, one would predict that increasing the level of either ZHX2 or p65 may rescue ccRCC cancer cell growth inhibited by XMU-MP-1." (PMID 38979373, 2025). "Although ZHX2 plays essential oncogenic roles in various cancers, its role in HCC is the opposite." (PMID 37563132, 2023). "Furthermore, the functions of ZHX2 in cancer cell development, including apoptosis, metastasis, proliferation, and immunoregulation, have been identified." (PMID 37563132, 2023).
cancer (continued). "Thus, understanding the role of ZHX2 in different types of cancers will be beneficial for cancer-targeting therapy." (PMID 35151335, 2022). "Besides the repression of AFP, ZHX2 also repressed the cancer biomarkers pyruvate kinase M1/2 (PKM) and hexokinase 2 (HK2) in HCC." (PMID 36232466, 2022). "Targeting ZHX2 has great potential in NK cell-based cancer immunotherapy." (PMID 36465389, 2022). "Second, the role of ZHX2 in cancers can be context dependent." (PMID 34779768, 2021). "The repertoire of different coactivators/repressors with which ZHX2 may interact can therefore govern its localization in the genome and thus its downstream function in different cancer settings." (PMID 34779768, 2021). "Although ZHX2 may be amplified in multiple cancers, its protein levels can be regulated post-transcriptionally." (PMID 34779768, 2021). "Conversely, cancer tissues with lower ZHX2 expression had higher LPL levels." (PMID 31740790, 2020). "These phenomena are consistent with the previous results that ZHX2 and HIFs may have some same mechanism in the process of promoting cancer." (PMID 32382017, 2020). "Moreover, based on the expression of ZHX2, clinicians may develop more effective, personalized approaches for cancer treatment." (PMID 37460540, 2023). "More importantly, the role of ZHX2 in other cancers, such as in TNBC, remains largely unknown." (PMID 34779768, 2021). "However, the role of ZHX2 in other cancers remains largely unclear." (PMID 34779768, 2021). "Thus far, it remains unclear which residues on ZHX2 are critical for its transcriptional activity as well as its oncogenic role in cancer." (PMID 34779768, 2021). "However, accumulating evidence suggests that ZHX2 may contribute to cancer pathology in other contexts." (PMID 34779768, 2021). "In the present study, the expressions of ZHX1 and ZHX3 were reduced in ccRCC, but the expression of ZHX2 was increased in ccRCC compared to the normal tissues, which suggests the expressions of ZHX family members are cancer type-specific." (PMID 28152006, 2017). "Since identifying different E/M states may predict the metastatic potential, future studies will be required to assess the existence and involvement of the mechanisms by which ZHX2 regulates E-cadherin expression in different TNBC molecular subtypes and other cancer types." (PMID 37460540, 2023). "Importantly, ZHX2 and MYC share coamplification in most cancer types observed." (PMID 34779768, 2021).
ZHX2 also shares sentences with these, for which no sentence is quoted: infection (6 papers); lymphoma (2); non-alcoholic fatty liver disease (2); acute liver failure (1); autism (1); B-cell lymphoma (1); bladder urothelial carcinoma (1); brain tumours (1); cardiac hypertrophy (1); cholangiocarcinoma (1); Cirrhosis (1); colorectal carcinoma (1); cryptococcosis (1); esophageal carcinoma (1); glomerulopathy (1); head and neck squamous cell carcinoma (1); hematological malignancies (1); Hepatic hemangioma (1); kidney chromophobe (1); kidney injury (1); lung adenocarcinoma (1); lung squamous cell carcinoma (1); mammary adenocarcinomas (1); myocarditis (1); neuroblastoma (1); ovarian carcinoma (1); pericarditis (1); prostate carcinoma (1); skin cutaneous melanoma (1); stomach adenocarcinoma (1).
A further 2 diseases each share a sentence with ZHX2 in 1 paper.